PRKCB (protein kinase C beta)
Description:
Calcium-activated, phospholipid- and diacylglycerol (DAG)- dependent serine/threonine-protein kinase involved in various cellular processes such as regulation of the B-cell receptor (BCR) signalosome, oxidative stress-induced apoptosis, androgen receptor-dependent transcription regulation, insulin signaling and endothelial cells proliferation. Plays a key role in B-cell activation by regulating BCR-induced NF-kappa-B activation. Mediates the activation of the canonical NF-kappa-B pathway (NFKB1) by direct phosphorylation of CARD11/CARMA1 at 'Ser-559', 'Ser-644' and 'Ser-652'. Phosphorylation induces CARD11/CARMA1 association with lipid rafts and recruitment of the BCL10-MALT1 complex as well as MAP3K7/TAK1, which then activates IKK complex, resulting in nuclear translocation and activation of NFKB1. Plays a direct role in the negative feedback regulation of the BCR signaling, by down-modulating BTK function via direct phosphorylation of BTK at 'Ser-180', which results in the alteration of BTK plasma membrane localization and in turn inhibition of BTK activity. Involved in apoptosis following oxidative damage: in case of oxidative conditions, specifically phosphorylates 'Ser-36' of isoform p66Shc of SHC1, leading to mitochondrial accumulation of p66Shc, where p66Shc acts as a reactive oxygen species producer. Acts as a coactivator of androgen receptor (AR)-dependent transcription, by being recruited to AR target genes and specifically mediating phosphorylation of 'Thr-6' of histone H3 (H3T6ph), a specific tag for epigenetic transcriptional activation that prevents demethylation of histone H3 'Lys-4' (H3K4me) by LSD1/KDM1A. In insulin signaling, may function downstream of IRS1 in muscle cells and mediate insulin-dependent DNA synthesis through the RAF1-MAPK/ERK signaling cascade. Participates in the regulation of glucose transport in adipocytes by negatively modulating the insulin-stimulated translocation of the glucose transporter SLC2A4/GLUT4. Phosphorylates SLC2A1/GLUT1, promoting glucose uptake by SLC2A1/GLUT1. Under high glucose in pancreatic beta-cells, is probably involved in the inhibition of the insulin gene transcription, via regulation of MYC expression. In endothelial cells, activation of PRKCB induces increased phosphorylation of RB1, increased VEGFA-induced cell proliferation, and inhibits PI3K/AKT-dependent nitric oxide synthase (NOS3/eNOS) regulation by insulin, which causes endothelial dysfunction. Also involved in triglyceride homeostasis (By similarity). Phosphorylates ATF2 which promotes cooperation between ATF2 and JUN, activating transcription. Phosphorylates KLHL3 in response to angiotensin II signaling, decreasing the interaction between KLHL3 and WNK4. Phosphorylates and activates LRRK1, which phosphorylates RAB proteins involved in intracellular trafficking. [Isoform Beta-II]: Acts as an activator of ferroptosis by mediating phosphorylation and activation of ACSL4. Also stimulates ferroptosis propagation by catalyzing phosphorylation of FOXK1, thereby promoting LGALS13 secretion.
Synonyms: PKC-beta; PKCB; PRKCB1; PKCβ; PKCI(2); PKCbeta; PRKCB2
Tractability: Small molecule: an approved drug acts on it; a high-quality ligand is known; it belongs to a druggable protein family. Antibody: its Gene Ontology location is reachable by antibodies, with high confidence; UniProt places it where antibodies can reach, with medium confidence. PROTAC: ubiquitination databases record sites on it; its protein half-life has been measured; a small molecule that binds it is known.
Target class: AGC protein kinase PKC family; AGC protein kinase PKC alpha subfamily; Enzyme; Kinase; AGC protein kinase group; Protein Kinase
Chemical probes: CHEMBL360304
Safety:
Unwanted effects reported when the protein is acted on. In parentheses: how it was acted on, where the effect was seen, and who reports it.
hyperglycemia (source: ClinPGx)
Gene: Protein-coding gene on chromosome 16 (23,835,959 to 24,220,611, forward strand). Ensembl gene ENSG00000166501.
Subcellular location: Cytoplasm; Nucleus; Membrane
Subcellular location (Human Protein Atlas): Nucleoplasm; Cytosol
Pathways (Reactome):
Signal Transduction: G alpha (z) signalling events; RHO GTPases Activate NADPH Oxidases; VEGFR2 mediated cell proliferation; WNT5A-dependent internalization of FZD4
Hemostasis: Disinhibition of SNARE formation; Response to elevated platelet cytosolic Ca2+
Cell Cycle: Depolymerization of the Nuclear Lamina
Gene expression (Transcription): RUNX1 regulates transcription of genes involved in differentiation of myeloid cells
Immune System: Activation of NF-kappaB in B cells
Neuronal System: Trafficking of GluR2-containing AMPA receptors
Gene Ontology:
Molecular function: calcium,diacylglycerol-dependent serine/threonine kinase activity; chromatin binding; histone binding; histone H3T6 kinase activity; nuclear androgen receptor binding; protein binding; protein kinase C binding; protein serine kinase activity; transcription coactivator activity; diacylglycerol-dependent serine/threonine kinase activity; protein serine/threonine kinase activity; ATP binding; calcium channel regulator activity; protein kinase activity; zinc ion binding
Biological process: negative regulation of dopamine receptor signaling pathway; protein kinase C signaling; regulation of D-glucose transmembrane transport; regulation of transcription by RNA polymerase II; B cell activation; B cell receptor signaling pathway; intracellular signal transduction; lipoprotein transport; mitotic nuclear membrane disassembly; negative regulation of D-glucose transmembrane transport; negative regulation of insulin receptor signaling pathway; positive regulation of angiogenesis; positive regulation of canonical NF-kappaB signal transduction; positive regulation of vascular endothelial growth factor receptor signaling pathway; protein phosphorylation; signal transduction; chromatin remodeling; phospholipase C-activating G protein-coupled acetylcholine receptor signaling pathway; positive regulation of DNA-templated transcription; regulation of synaptic vesicle exocytosis; regulation of transport
Cellular component: cytoplasm; extracellular exosome; nucleoplasm; nucleus; plasma membrane; cytosol; calyx of Held; membrane; presynaptic cytosol; spectrin
Genetic constraint (gnomAD): Loss-of-function variants: 12 observed, 80.75 expected, observed/expected ratio (o/e) 0.15, 90% interval 0.094 to 0.24. The upper end of that interval is the gene's LOEUF score, 0.24, which puts it in group 1 of 6, group 1 being the genes least tolerant of losing a copy. Missense variants: 499 observed, 890.07 expected, observed/expected ratio (o/e) 0.56, 90% interval 0.52 to 0.6. Synonymous variants: 333 observed, 331.65 expected, observed/expected ratio (o/e) 1, 90% interval 0.92 to 1.1.
Homologues: Orthologues: chimpanzee PRKCB (100% identical), macaque PRKCB (99% identical), dog PRKCB (99% identical), mouse Prkcb (99% identical), rat Prkcb (99% identical), pig PRKCB (99% identical), tropical clawed frog prkcb (91% identical), guinea pig PRKCB (89% identical), zebrafish prkcbb (87% identical), rabbit PRKCB (86% identical), zebrafish prkcba (78% identical), Caenorhabditis elegans pkc-2 (67% identical), and 6 more. Paralogues in human: PRKCA (80% identical), PRKCG (70% identical), PRKCE (37% identical), PRKCH (36% identical), PKN2 (33% identical), PRKCZ (32% identical), PRKCI (32% identical), PKN1 (31% identical), PKN3 (30% identical).
Diseases named in the same sentence as PRKCB in open-access papers:
PRKCB is named in the same sentence as 188 diseases in open-access papers, as found by Europe PMC text mining. Sharing a sentence is not in itself a finding about the gene and the disease. The quoted sentences say what the papers report.
Hyperglycemia (45 papers, 2007 to 2025). An increased concentration of glucose in the blood. "The protein encoded by PRKCB has been reported to be involved in many different cellular functions, which associate with tumorigenesis, insulin resistance and diabetic problems such as hyperglycemia-evoked blood-brain barrier damage, as well as diabetic nephropathy and retinopathy." (PMID 27055244, 2016). "Hyperglycemia also promotes proinflammatory responses via the activation of protein kinase C-beta and aldose reductase." (PMID 38397984, 2024). "Expression of CDH5, CTNNB1, and PRKCB was checked in the hyperglycemia disease model, and we observed that PRKCB was localized extensively in the membrane, while the signals of CDH5 and CTNNB1 were diffused and not exclusively on the membrane." (PMID 34180064, 2021). "Taken together, this indicated that VEAL2 can modulate PRKCB activity and restrict translocation of PRKCB to the cell membrane in hyperglycemia, mitigating subsequent turnover of junctional complexes and maintaining endothelial cell integrity." (PMID 34180064, 2021). "Moreover, hyperglycemia activates protein kinase C-beta (PKC-β) via diacylglycerol (DAG), which inhibits eNOS, reduces NO production, and causes vascular dysfunction, but it promotes mesangial cell proliferation and basement membrane collagen synthesis." (PMID 41030326, 2025).
diabetes (43 papers, 2007 to 2025). "Examples include as follows: (a) NEUROD1 which encodes a transcription factor that is involved in the development of the endocrine cell lineage and has been implicated in monogenic diabetes, (b) PRKCB involved in insulin resistance and (c) GNAS, implicated in beta-cell proliferation." (PMID 30914061, 2019). "The top two predictors of age were on the PRKCB and REG4 genes, which are associated with diabetes and cancer, respectively." (PMID 29754148, 2018).
breast carcinoma (22 papers, 2006 to 2025). "The increased expression of PRKCB is seen as advantageous and has been linked to improved relapse-free survival for individuals with breast cancer." (PMID 38606198, 2024). "Protein kinase C beta (PKCβ) expression in breast cancer is associated with a more aggressive tumor phenotype, yet the mechanism for how PKCβ is pro-tumorigenic in this disease is still unclear." (PMID 24795864, 2014). "All genes, with exception of PRKCB, had significantly higher levels of DNA methylation in breast cancer samples compared to controls." (PMID 33499882, 2021). "PRKCB was reported to enhance the expression of cyclin D1 in human breast cancer cells, leading to cell proliferation and cell cycle progression." (PMID 28422739, 2017). "Increased PRKCB in breast tumor stroma versus normal stroma was confirmed in a breast cancer patient cohort." (PMID 24795864, 2014). "In this dataset, PRKCB is significantly increased in breast cancer stroma versus normal confirming the translational relevance of PKCβ in the breast TME." (PMID 24795864, 2014). "This increase in stromal PRKCB is similarly observed in a human breast cancer patient cohort confirming the translational relevance of PKCβ function in the TME." (PMID 24795864, 2014). "Methylation pattern of MAST1, PRDM14, and ZNF177 may represent new diagnostic biomarkers for breast cancer, while methylation of ADCY4, CPXM1, DNM3, PRDM14, PRKCB, and ZNF177 may hold prognostic potential for breast cancer." (PMID 33499882, 2021). "While there are reports indicating that PRKCB can promote mammary tumorigenesis, enhance breast cancer cells growth and cyclin D1expression, and has the potential as therapeutic target, there is also a report indicating it may inhibit tumor growth and metastasis." (PMID 32005108, 2020). "The β isoforms of PKC (PRKCB) might play significant roles in promoting human breast cancer growth." (PMID 26267321, 2015). "The expression levels of Prss14/epithin (ST14), PKCβ (PRKCB), and three JNKs (MAPK8, MAPK9, and MAPK10) in more aggressive ER-negative (ER−) and less aggressive ER-positive (ER+) breast cancer patients were compared individually in the plot." (PMID 32241917, 2020). "Taking these analyses into consideration, we propose that PRKCB and MAPK9 can be additional prognosis markers and can be used in precision medicine for breast cancer patients." (PMID 32241917, 2020). "For luminal A breast cancer, we observed that genes associated with favourable prognosis—including key regulators of glucose metabolism HK3, LDHAL6A, apoptosis regulator PRKCB, and alcohol dehydrogenase ADH6—are not directly targeted by current treatments." (PMID 41007296, 2025). "For example, tamoxifen, an FDA-approved inhibitor of the protein kinase C genes PRKCB and PRKCE, currently used for breast cancer treatment, could potentially be used to target EGFR or KRAS-mutated lung cancers and NRAS-mutated skin cancer." (PMID 37863651, 2024). "Moreover, we found six sex-biased genes (EGFR, CDK6, PRKCB, PDCD1, KCNH2, FCGR3B, and TOP2A) in BRCA were the therapeutic targets of breast cancer." (PMID 39175079, 2024). "To further explore the clinical value of these biomarkers, we evaluated whether 6 of our differentially methylated genes—ADCY4, CPXM1, DNM3, PRDM14, PRKCB, and ZNF177—had any relation with overall survival of breast cancer patients." (PMID 33499882, 2021). "Moreover, we showed that DNA methylation landscape of ADCY4, CPXM1, DNM3, PRDM14, PRKCB, and ZNF177 could be selected as accurate biomarkers for the prognosis of breast cancer." (PMID 33499882, 2021). "On the other hand, the role of PRKCB in breast cancer progression is still not clearly defined." (PMID 32005108, 2020).
diabetic nephropathy (15 papers, 2008 to 2025). "Our data showed that in comparison to the control group, EIF4B, RICTOR, and PRKCB displayed markedly higher mRNA expression in diabetic nephropathy rats." (PMID 35620059, 2022). "Meanwhile, Western blot results confirmed the significant up-regulation of EIF4B, RICTOR, and PRKCB proteins in kidney tissues of diabetic nephropathy rats than that of control rats." (PMID 35620059, 2022). "Although the expression of EIF4B, RICTOR, and PRKCB was verified in a diabetic nephropathy rat model, a deeper analysis should be conducted for confirming their functions in diabetic nephropathy progression." (PMID 35620059, 2022). "Differentially expressed marker genes of immune cells EIF4B, RICTOR, and PRKCB were significantly enriched in the mTOR pathway, which were confirmed to be up-regulated in diabetic nephropathy." (PMID 35620059, 2022). "The GSE111154 and GSE142025 datasets were utilized for validating the expression of mTOR pathway markers EIF4B, RICTOR, and PRKCB in the kidneys from controls and diabetic nephropathy patients." (PMID 35620059, 2022). "The expression of mTOR pathway markers EIF4B, RICTOR, and PRKCB was verified in kidney tissues from the control group and the diabetic nephropathy rat model group." (PMID 35620059, 2022). "To verify the expression of EIF4B, RICTOR, and PRKCB proteins, we established a diabetic nephropathy rat model." (PMID 35620059, 2022). "Besides, evidence shows that PRKCB upregulated at the gene expression level in diabetic nephropathy, proven to be a predictor for worsening of kidney disease in subjects with type 2 diabetes." (PMID 40290492, 2025). "Collectively, marker genes of immune cells EIF4B, RICTOR, and PRKCB in the mTOR pathway might participate in diabetic nephropathy progression." (PMID 35620059, 2022). "Also, we established diabetic nephropathy rat models; marker genes (EIF4B, RICTOR, and PRKCB) of the immune cells were confirmed to be up-regulated in diabetic nephropathy." (PMID 35620059, 2022).
Obesity (14 papers, 2013 to 2025). Accumulation of substantial excess body fat. "PRKCB deficiency reduces the obesity syndrome of mice, while RAB3A is involved in the regulation of insulin secretion." (PMID 37620670, 2023). "Of these genes, we found that the expression level of protein kinase C beta (PRKCB) was high in obesity but low in COPD." (PMID 37886639, 2023). "As one of the 18 overlapping DEGs in obesity and COPD, PRKCB (encoded PKCβprotein) had the PPI with BMPR2." (PMID 37886639, 2023).
cardiac hypertrophy (13 papers, 2005 to 2025). "A recent study has observed interaction between phosphoinositide 3-kinase (PI3K)-Akt signaling pathway, which is known to cause physiological cardiac hypertrophy, and protein kinase C beta (PKCβ) 2, which is known to cause pathologic cardiac hypertrophy." (PMID 34646605, 2021). "Sodium ferulate has been shown to mitigate myocardial hypertrophy induced by abdominal aorta coarctation by inhibiting protein kinase C beta (PKC-β) and activating the MAPK signaling pathways." (PMID 40235541, 2025).
colon cancer (13 papers, 2011 to 2024). "They identified PRKCB promoter hypermethylation in LUAD, colon cancer and rectal cancer, showing PRKCB as an epigenetically-silenced gene in Wnt pathway." (PMID 28422739, 2017). "Also, in colon cancer, PRKCB level was reported to be either elevated, lowered or not changed." (PMID 35174160, 2021).
atherosclerosis (11 papers, 2016 to 2023). A disease characterized by the build-up of fatty material and calcium deposition in the arterial wall resulting in partial or complete occlusion of the arterial lumen. "However, the characteristics of PRKCB that plays a pro-inflammatory role in endothelial cells and promotes VSMC proliferation and migration are associated with pro-atherosclerosis as observed in PRKCB knockout mice." (PMID 30885136, 2019).
endothelial dysfunction (9 papers, 2018 to 2026). In vascular diseases, endothelial dysfunction is a systemic pathological state of the endothelium (the inner lining of blood vessels) and can be broadly defined as an imbalance between vasodilating and vasoconstricting substances produced by (or acting on) the endothelium. "ApoC-III activates protein kinase C beta (PKC β) which inhibits insulin signaling in ECs through eNOS pathway and the production of NO in ECs, thus determining endothelial dysfunction." (PMID 36689070, 2023).
glioma (9 papers, 2014 to 2025). A benign or malignant brain and spinal cord tumor that arises from glial cells (astrocytes, oligodendrocytes, ependymal cells). "Specifically, genes such as PRKCB have been found to be expressed in pathways including oocyte meiosis, suggesting a potential role in glioma development." (PMID 39975150, 2025). "PRKCB is involved in pathways related to neurological function and carcinogenic processes, including the glioma, MAPK, and Rap1 signalling pathways." (PMID 38606198, 2024). "We found two new occurrences of PRKCA (protein kinase C, alpha) fusions in lung squamous cell carcinoma and three PRKCB (protein kinase C, beta) fusions in lung squamous cell carcinoma, lung adenocarcinoma and low-grade glioma." (PMID 25204415, 2014).
melanoma (9 papers, 2008 to 2023). A malignant, usually aggressive tumor composed of atypical, neoplastic melanocytes. "PRKCB encodes a serine and threonine-specific protein kinase involved in many different cellular functions, such as neutrophil chemotaxis, melanoma cell growth and proliferation, or induction of apoptosis in endothelial cells." (PMID 37273692, 2023). "In the present study, we first screened for any differences in the mRNA expression of the genes encoding these five PKC isozymes (PRKCD, PRKCA, PRKCB, PRKCE and PRKCI) between the BRAFi-sensitive and BRAFi-R melanoma cell lines." (PMID 36551563, 2022). "PRKCB is frequently mutated and its expression is often lost in melanoma, but the impact of these mutations on PKCβ activity has not been evaluated." (PMID 35158973, 2022).
autism (8 papers, 2007 to 2025). Persistent deficits in social interaction and communication and interaction as well as a markedly restricted repertoire of activity and interest as well as repetitive patterns of behavior. "Similarly, an analysis of chromosome 16p revealed an association between autism and the protein kinase c-beta gene (PRKCB1), which is expressed in granule cells of the brain and B lymphocytes." (PMID 18053270, 2007).